DPP4 (dipeptidyl peptidase 4)
Diseases named in the same sentence as DPP4 in open-access papers (continued):
Sharing a sentence is not in itself a finding about the gene and the disease.
breast carcinoma (continued). "Additionally, a study on breast cancer, indicated that FAP+PDGFRβ+ CAF in tissues not only released CXCL12 to promote the migration of CD4+CD25+ T cells, but also expressed CD73, dipeptidyl peptidase IV (DPP4) and B7H3 to promote the conversion of CD4+ T cells to FOXP3+ Treg cells." (PMID 36759842, 2023). "Retrospective analysis data represents that breast cancer-bearing diabetic patients taking metformin had significant OS benefit either with or without DPP-4 inhibitors, whereas DPP-4 inhibitors alone displayed a worse trend." (PMID 34063285, 2021). "This family comprises seven members, including DPP3, DPP4, DPP6, DPP7, DPP8, DPP9, and DPP10; however, information on the involvement of DPPs in breast cancer is lacking in the literature." (PMID 34359286, 2021).
Stroke (65 papers, 2014 to 2026). Sudden impairment of blood flow to a part of the brain due to occlusion or rupture of an artery to the brain. "Our findings also clarify the causal mechanisms of DPP4 gene expression at the mRNA level on other CVDs, such as AF, MI, and stroke." (PMID 40904650, 2025). "Our previous study further indicated that DPP-4 inhibitor use in insulin-treated patients with T2D was linked to a lower stroke risk compared with non-DPP-4 inhibitor use." (PMID 41011236, 2025). "The results show that the use of DPP4 inhibitors and the history of cerebrovascular accident were significantly associated with an increased risk of thrombotic events or acute arterial embolism (p = 0.023 and p = 0.031, respectively)." (PMID 37374918, 2023). "The logistic regression analysis revealed that the age, prior DPP4 inhibitor use, and a history of stroke were significantly associated with an increased risk of developing thromboembolic events." (PMID 37374918, 2023). "In contrast to the EMPA‐REG OUTCOME trial, reporting non‐significant higher stroke risk (HR 1.24 [95% CI 0.92‐1.67]), we report a lower risk association for stroke (HR 0.79 [95% CI 0.61‐1.03]) with dapagliflozin compared with DPP‐4 inhibitor treatment." (PMID 28771923, 2018). "Previous meta-analyses on SGLT2-Is, GLP1-RAs, and DPP4-Is yielded discordant results for the risk of MACEs and stroke." (PMID 41542235, 2024). "Indeed, previous work from our group has shown that a prolonged treatment with the GLP1- agonist Exendin-4 and the DPP-4 inhibitor Linagliptin initiated after stroke, improved stroke recovery in association with normalized glucose metabolism." (PMID 38424560, 2024). "Studies of DPP4 inhibitors in diabetic patients have shown a reduced risk of stroke." (PMID 35627909, 2022). "DPP-4 inhibitor-medicated increased GLP-1 may have a direct effect at the neuronal level of brain which was suspected to be associated with the neuroprotective effect on the stroke mice." (PMID 29301579, 2018). "Multivariate MR within the GRAPPLE framework revealed the impact of specific candidates like SLC4A10, BMI, TC, HTN, and TG on the MI and stroke pathways from DPP4 gene expression at the mRNA level." (PMID 40904650, 2025). "In this context, dual-specific inhibitors of APN/DPP4 have been developed and have been proven to be effective in vitro and in vivo, e.g., in mouse models of multiple sclerosis or stroke." (PMID 36979703, 2023). "DPP4 inhibitors have previously been administered in several rodent models of stroke and have demonstrated efficacy in reducing injury and enhancing functional recovery." (PMID 37280551, 2023). "Our findings that increased s-DPP4 (a potential consequence of DPP4 inhibition), was predictive of better cognitive function corroborate prior findings in the stroke and cognition literature." (PMID 37280551, 2023). "In contrast, SDRs were detected with DPP-4 inhibitors in all cardiovascular events except for a stroke." (PMID 36078917, 2022). "Glucagon-like peptide 1 receptor agonists and dipeptidyl-peptidase 4 inhibitors are very interesting in this respect since many preclinical studies have shown their positive effects on stroke recovery." (PMID 34937562, 2021). "Experimental animal studies have also shown that acute treatment with GLP-1 analogues and dipeptidyl peptidase-4 (DPP-4) inhibitors after a stroke is neuroprotective including better recovery, as recently reviewed." (PMID 31307484, 2019). "Patients diagnosed with renal disease, coronary heart disease and stroke were 4.20 (p < 0.0001) and 2.22 (p < 0.0001) times more likely to be prescribed DPP-4 inhibitors as first-line outpatient treatment for T2DM." (PMID 31695754, 2019). "These positive or neutral results on AF risk raised the question of potentially protective effects of DPP-4 inhibitors against stroke." (PMID 31540142, 2019).
Stroke (continued). "DPP-4 inhibitors were prescribed over metformin in patients with renal disease (odds ratio [OR]: 4.20; p < 0.0001), coronary heart disease and stroke (OR: 2.22; p < 0.0001)." (PMID 31695754, 2019). "However, evaluations revealed potential pathways between DPP4 gene expression at the mRNA level and MI, as well as DPP4 gene expression at the mRNA level and stroke." (PMID 40904650, 2025). "Overall, we found that DPP-4 inhibitors did not significantly reduce all-cause mortality, HF, MACEs, MI, or stroke when compared with the control group over the 24- to 302-week study period." (PMID 40832578, 2025). "However, the evidence was inconclusive regarding relationships between DPP4 levels and other CVDs (AF, MI, and stroke), despite the potential pleiotropic pathway from DPP4 levels to MI and stroke." (PMID 40904650, 2025). "Also, the one-component BESIDE-MR produced similar results to GRAPPLE for the pathway from DPP4 gene expression at the mRNA level to MI and stroke." (PMID 40904650, 2025). "Dipeptidyl peptidase 4 inhibitors did not significantly increase the risk of stroke compared with controls (OR= 1.01; 95% CI, 0.78–1.30), and there was no heterogeneity (I2 = 39.8%, P = 0.056)." (PMID 40832578, 2025). "While sulfonylureas may increase the risk of hypoglycemia and mortality when combined with insulin, metformin enhances insulin sensitivity, and DPP-4 inhibitors have shown protective effects against stroke." (PMID 41011236, 2025). "The results based on GTEx show that DPP4 inhibition was not causal to the risk of all-cause HF (OR: 0.45; CI, 0.15–1.31), AF (OR: 1.97; CI, 0.87–4.51), MI (OR: 2.89; CI: 0.07–127.46), and stroke (OR: 0.78; CI, 0.03–20.70)." (PMID 40904650, 2025). "The results from the MR estimates suggest that DPP4 gene expression at the mRNA level has no causal relationship with AF, MI, and stroke." (PMID 40904650, 2025). "Dipeptidyl peptidase 4 inhibitors appear neutral in stroke prevention." (PMID 38791064, 2024). "The review findings indicate that GLP1-RAs, but not SGLT2-Is or DPP4-Is, decrease non-fatal stroke risk in diabetic people." (PMID 41542235, 2024). "We have shown in previous studies that the DPP-4 inhibitor Linagliptin enhances the number of stroke-induced DCX+ neuroblasts in association with improved stroke recovery, even though T2D per se did not affect this cellular process." (PMID 38424560, 2024). "Similarly, dipeptidyl peptidase-4 inhibitor (DPP4I) use has been reported to reduce the risk of major cardiovascular adverse events, including stroke, though its effect on heart failure remains controversial." (PMID 35142921, 2023). "DPP-4 inhibitors (0.84; 0.82–0.86), metformin (0.90; 0.89–0.91), insulin (0.92; 0.91–0.93) and sulfonylureas (0.98; 0.96–0.99) also showed moderately reduced HR for stroke/TIA." (PMID 35933524, 2022). "This study tested the hypothesis that abrogated dipeptidyl peptidase-4 (DPP4) activity played a crucial role on reducing stroke volume and preserving neurological function in rodent after acute hemorrhagic stroke (AHS)." (PMID 33162819, 2020). "None of the cardiovascular outcome trials with DPP-4 inhibitors identified a reduced risk for stroke with any of these medications." (PMID 31540142, 2019). "Similar to the case with other drugs, none of the cardiovascular outcome trials or meta-analyses with DPP-4 inhibitors published so far have differentiated between stroke events of hemorrhagic or ischemic origin, least of all between atherothrombotic or thromboembolic events." (PMID 31540142, 2019). "Furthermore, in a review of 115 randomised, controlled trials, SU was associated with an increased mortality (OR 1.22), stroke (OR 1.28), and MACCE (OR 1.85, if only the comparison with DPP-4 inhibitors was considered)." (PMID 25645672, 2015).
Stroke (continued). "Our findings, based on a series of robust to weak IVs and genetic heterogeneity MR analyses, suggest that increased DPP4 gene expression at the mRNA level may be causally linked to HF but not to AF, MI, or stroke in individuals of European ancestry." (PMID 40904650, 2025). "However, there was limited evidence that increased DPP4 levels affect AF, MI, or stroke." (PMID 40904650, 2025). "Metformin monotherapy may reduce stroke risk, while dipeptidyl peptidase 4 inhibitors, sodium-glucose co-transporter 2 inhibitors, and insulin do not seem to affect the incidence of stroke." (PMID 39407846, 2024). "Moreover, strokes occurred in 161 (6.5%) DPP-4 inhibitor users and in 149 (6.0%) metformin users." (PMID 36078917, 2022). "However, the reasons for the use of DPP-4 inhibitors over metformin in patients with coronary heart disease and stroke remains unclear." (PMID 31695754, 2019). "Moreover, stroke-mediated damage could increase the permeability of the BBB which may have a influence on DPP-4 inhibitors for neuroprotection." (PMID 29301579, 2018). "The use of GLP1-RAs, but not SGLT2-Is or DPP4-Is, may decrease non-fatal stroke risk." (PMID 41542235, 2024). "The DPP-4 substrate SDF-1α plays a pivotal role in the brain, as it regulates neurovascular remodeling after stroke." (PMID 29776406, 2018). "Therefore, the inhibitory effect of AMD 3100 over linagliptin on stroke outcome could not be linked to altered DPP-4 activity between the groups." (PMID 29776406, 2018). "A meta-analysis found that although SGLT2i was more appropriate for type 2 diabetes patients who were at high risk of stroke compared to dipeptidyl peptidase 4 inhibitor (DPP-4i), the results of this study showed that SGLT2i did not reduce the risk of stroke." (PMID 39247919, 2024). "First, we focus on soluble dipeptidyl peptidase 4 (s-DPP4) and C–C motif chemokine 11 (CCL11) as biomarkers and potential therapeutics for post-stroke cognition that have been previously reported on in the context of stroke and in cognition." (PMID 37280551, 2023). "Sulfonylureas, dipeptidyl peptidase-4 inhibitors (DPP-4i) and SGLT2 inhibitors (SGLT2i) lacked evidence of reduced stroke risk in RCT." (PMID 35933524, 2022). "Recent meta-analyses have also found that DPP-4 inhibitors do not affect the risk for CVD mortality and stroke." (PMID 30622967, 2018). "Although DPP-4 inhibitors are known to have favorable effects on cardiovascular disease, such as aortic aneurysm and stroke, the effect of DPP-4 inhibitors on myocarditis has not been investigated." (PMID 25768281, 2015). "Our investigation demonstrated that administration of DPP-4 inhibitors in individuals afflicted with T2DM does not notably elevate the cardiac risk within this demographic, inclusive of MI, MACE, HF, and all-cause mortality as well as stroke events." (PMID 40832578, 2025). "Interestingly, DPP-4 inhibitors improve neurological prognosis after stroke in rodents, independent of GLP-1, possibly by increasing the bioavailability of other bioactive DPP-4 substrates, such as stromal cell-derived factor-1α." (PMID 37025208, 2023). "The inclusion in our network analysis of the AMPLITUDE-O and EMPEROR-P data have modified the conclusions of the most recent similar analysis indicating that SGLT-2 inhibitors increased the risk of stroke as compared with GLP-1RA and that GLP-1RA are superior to DPP-4 inhibitors as for nonfatal MI." (PMID 35296336, 2022). "SGLT-2 inhibitors and GLP-1RA are superior to DPP-4 inhibitors in reducing the risk of most cardiorenal outcomes; SGLT-2 inhibitors are superior to GLP-1RA in reducing the risk of HHF and renal events; GLP-1RA only reduced the risk of nonfatal stroke." (PMID 35296336, 2022).
Stroke (continued). "The observed trend toward less stroke risk with GLP1-RAs use perhaps might be explained by the fact that GLP1 receptors are expressed in a wider range of the body, such as the brain, the heart, and the pancreas, and that GLP1-RAs, unlike DPP4-Is, cross the blood–brain barrier." (PMID 41542235, 2024). "Although the mechanism of action of DPP4i is similar to that of GLP1RA, DPP‐4 does not cross the BBB and does not induce plasma GLP‐1 elevation, which may be why DPP4i does not show a beneficial effect on stroke." (PMID 39789833, 2025).
Hepatic steatosis (59 papers, 2010 to 2025). Steatosis is a term used to denote lipid accumulation within hepatocytes. "Liver expresses and secretes DPP4, and the hepatic DPP4 expression levels are associated with a degree of hepatic steatosis in patients with NASH9,10." (PMID 33173107, 2020). "Hepatocyte‐specific DPP4 overexpression in mice increases body fat and promotes hepatic steatosis, suggesting that this association is causative." (PMID 30824564, 2019). "Further studies are required to find the potential direct effects of DPP-4 inhibition on these genes associated with hepatic steatosis." (PMID 22761701, 2012). "In addition, proinflammatory cytokine expression and the extent of hepatic steatosis were lower in the livers of DPP-4-deficient rats compared to wild-type rats." (PMID 38131990, 2023). "Moreover, DPP-4 deficient rats showed lower levels of hepatic pro-inflammatory and pro-fibrotic cytokines and reduced hepatic steatosis compared to wild-type rats." (PMID 35163991, 2022). "However, decreased hepatic dpp4 expression was associated with a reduced expression of genes involved in lipid metabolism and reduced signs of hepatic steatosis and finally resulted in a reduction of circulating total cholesterol concentrations." (PMID 31794591, 2019). "SGLT2 inhibitors promote hepatoprotection through Akkermansia-enriched remodeling, while thiazolidinediones and DPP-4 inhibitors have neutral or harmful effects on hepatic steatosis." (PMID 41170420, 2025). "DNA methylation affecting the hepatic expression of dipeptidyl peptidase 4 (DPP4) can worsen the development of liver steatosis affecting hepatic insulin signalling and decreasing GLP‐1 levels." (PMID 40371883, 2025). "Here, we investigate the role of hepatic DPP4 in ventricular function and preventing cardiac inflammation and fibrosis in a diet‐induced model of hepatic steatosis." (PMID 40771104, 2025). "DPP4 inhibitors, such as sitagliptin and gemigliptin, have shown potential in ameliorating hepatic steatosis and inflammation in MASLD by modulating glucose metabolism and inflammatory pathways." (PMID 39941272, 2025). "The primary outcome was the change in the fatty liver index (FLI) assessed using a linear mixed-effects model from the initiation of SGLT2 or DPP4 inhibitors." (PMID 38114769, 2024). "It should be noted, though, that the effects of DPP4 inhibitor therapies on hepatic steatosis (including inflammatory markers and fibrosis in MAFLD) are relatively small and questionable." (PMID 37367914, 2023). "Consistent with this, hepatocyte-specific overexpression of DPP4 in mice results in increased hepatic steatosis, liver enzymes, and markers of inflammation." (PMID 36472923, 2023). "Only a limited number of studies have evaluated in humans the impact of GLP-1RA or DPP-4 inhibitors on liver function and hepatic steatosis." (PMID 32823659, 2020). "In the present study, we investigated the effects of a DPP-4 inhibitor, linagliptin, on hepatic steatosis in OSI-906-treated mice." (PMID 33105604, 2020). "We previously reported that DPP-4 inhibition prevented diet-induced hepatic steatosis and adipose tissue inflammation in a diabetic mouse model." (PMID 33105604, 2020). "DPP-4 inhibitors have been reported to decrease lipid accumulation in HFD-induced hepatic steatosis." (PMID 32937958, 2020). "We also reported that DPP-4 inhibition prevented diet-induced adipose tissue inflammation and hepatic steatosis in diabetic mice." (PMID 33105604, 2020). "Taken together, these results show an effect of DPP-4 inhibition on hepatic steatosis that is induced by the acute inhibition of IR/IGF1R signaling through an insulin signaling-independent pathway." (PMID 33105604, 2020). "In this study, we reported that the DPP-4 inhibitor linagliptin ameliorated hepatic steatosis elicited by the dual IR/IGF1R inhibitor OSI-906." (PMID 33105604, 2020).